CDKN1A (cyclin dependent kinase inhibitor 1A)
Diseases named in the same sentence as CDKN1A in open-access papers (continued):
Sharing a sentence is not in itself a finding about the gene and the disease.
ovarian carcinoma (58 papers, 2008 to 2025). A malignant neoplasm originating from the surface ovarian epithelium. "The cancer-associated fibroblast-derived exosome miR-98-5p increases ovarian cancer cell proliferation and promotes cisplatin resistance by targeting CDKN1A." (PMID 36439168, 2022). "Exosomes derived from CAFs contain overexpressed miR-98-5p, which has been shown to enhance cisplatin resistance in ovarian cancer by downregulating cyclin-dependent kinase inhibitor 1A (CDKN1A)." (PMID 40757000, 2025). "There are also a study suggesting that overexpression of CDKN1A can induce apoptosis in ovarian cancer cells." (PMID 39650552, 2024). "For instance, Wanget al. revealed that miR-149-3p promoted resistance to DDP in ovarian cancer by regulating CDKN1A and TIMP2." (PMID 38477044, 2024). "While CAFs-derived exosome microRNA-98-5p (miR-98-5p) can promote CDDP resistance in ovarian cancer by downregulating monoclonal antibody to cyclin-dependent kinase inhibitor 1A (CDKN1A)." (PMID 37666813, 2023). "MiR-98-5p is an exosomal miRNA derived from CAFs and promotes cisplatin resistance in ovarian cancer cells by targeting CDKN1A to inhibit CDKN1A expression." (PMID 36439168, 2022). "Exosomal miR-98-5p from CAFs enhanced cisplatin (DDP) resistance via downregulation of cyclin-dependent kinase inhibitor 1A (CDKN1A) in subcutaneous-ovarian-cancer-bearing nude mice." (PMID 35024437, 2022). "Guo's studies have illustrated that cancer-associated fibroblast- derived exosomal who carrying overexpressed miR-98-5p promoted cisplatin resistance in ovarian cancer by downregulating CDKN1A." (PMID 35578599, 2022). "In contrast, some studies also indicated that low expression level of CDKN1A was correlated with better survival in cervical, gastric, cholangiocarcinoma, and ovarian cancers." (PMID 35186763, 2022). "Another study has shown that CDKN1A overexpression increased the proportion of the G0/G1 phase cells, decreased that of the S phase cells, and elevated cell apoptosis in ovarian cancer cells." (PMID 34195287, 2021). "Knocking out CDKN1A promoted cisplatin resistance in ovarian cancer cells, increasing ovarian cancer cell proliferation and decreasing apoptosis in previously cisplatin-sensitive cells." (PMID 33808627, 2021). "MiR-141/KLF12/Sp1/survivin signaling pathway enhanced AR in ovarian cancer, and a transcriptomic study addressed the importance of CDKN1A-regulated quiescence for cells to survive from anoikis in head and neck squamous carcinoma." (PMID 34456997, 2021). "This study helped illustrate a potential mechanism by which CAFs promote therapeutic resistance via miR-98-5p-mediated CDKN1A inhibition in ovarian cancer." (PMID 33808627, 2021). "The bioinformatic data revealed four genes (i.e., guanosine 5′-monophosphate synthase (GMPS), progesterone receptor (PR), CD40, and p21 (cyclin-dependent kinase inhibitor 1A)) to play an important role in ovarian cancer progression." (PMID 30701134, 2019). "Consistent to our findings, p21 (CDKN1A) is reported to increase after paclitaxel treatment in ovarian cancer cells contributing to cell cycle regulation." (PMID 26964739, 2016). "In the discovery set, SNPs in several genes were found to be associated with the risk of ovarian cancer; of these, five genes (ABL1, CCND3, CDKN1A, E2F3 and CDK2) were significant in log-additive models (P-value <0.05)." (PMID 19738611, 2009). "Furthermore, miR-149-3p was shown to inhibit EMT by targeting TIMP metallopeptidase inhibitor 2 (TIMP2) and cyclin-dependent kinase inhibitor 1A (CDKN1A) mRNAs in ovarian cancer." (PMID 38396852, 2024). "Furthermore, kaempferol amplified the effect of cisplatin by down-regulating ABCC6 and cMyc expression, while up-regulating CDKN1A expression to advance apoptosis in OVCAR-3 human ovarian cancer cells." (PMID 38143502, 2023).
ovarian carcinoma (continued). "Additionally, it has been observed that exosomes loaded with miR-98-5p secreted by CAFs increase cell proliferation, inhibit apoptosis, and promote cisplatin resistance in ovarian cancer cells by downregulating cyclin-dependent kinase inhibitor 1A (CDKN1A)." (PMID 37168385, 2023). "Then, to determine whether bexarotene acted as an RXR agonist in ovarian cancer cell lines, we measured the CDKN1A mRNA expression levels after 24 h of bexarotene treatment." (PMID 35778597, 2022). "CDKN1A was highly expressed in cisplatin-sensitive ovarian cancer cell lines, and silencing CDKN1A significantly promoted the proliferation and entry into the cell cycle of cisplatin-sensitive ovarian cancer cells and reduced apoptosis." (PMID 36439168, 2022). "Another recent study performed in ovarian cancer cell lines showed the overexpression of PKM2 that in turn increased CCND1 expression, whereas it decreased CDKN1A expression; determinants involved in the increase of proliferation and in the decrease of apoptosis of ovarian cancer cells." (PMID 32326107, 2020). "Ectopic overexpression of miR-572 promoted ovarian cancer cell proliferation and cell cycle progression in vitro and tumorigenicity in vivo by inhibiting its direct target suppressor of cytokine signaling 1 and cyclin-dependent kinase inhibitor 1A (p21KIP)." (PMID 30863671, 2019). "LncRNA FAL1 was amplified in more than 30% of ovarian cancers, which could promote cell proliferation by recruiting the chromatin repressor protein BMI‐1 and inhibiting the expression of CDKN1A." (PMID 30216655, 2018). "For example, lncRNA FAL1 amplified in ovarian cancers could promote cell proliferation by recruiting the chromatin repressor protein BMI‐1 and inhibiting the expression of CDKN1A." (PMID 30216655, 2018). "Co-treatment of VPA with DOX led to synergistic suppression of cell viability with an increase in caspase-3 activity and CDKN1A, CCNE1, PARP1, and PARP3 proteins expression in ovarian cancer cell lines." (PMID 28498322, 2017). "For example, PKM2 promotes ovarian cancer growth though regulating CCND1 and CDKN1A expression." (PMID 35242214, 2022). "In the context of ovarian cancer, it is revealed that CAF-derived exosomes carrying overexpressed miR-98-5p could promote cisplatin resistance of cancer cells by downregulating cyclin-dependent kinase inhibitor 1 A (CDKN1A)." (PMID 35488263, 2022). "Members of the FOXO subfamily were previously shown to cooperate with SMAD2/3–SMAD4 to induce CDKN1A (also called p21Cip1) in epithelial cells in response to TGF-β, and FOXO3 has previously been shown to cooperate with the SMADs to regulate cyclin induction in ovarian cancer." (PMID 35302162, 2022). "Our candidates also included several genes typically considered TSGs, including CDKN1A (bladder carcinoma, 9.2% in TCGA), KMT2A (kidney carcinoma, 0.6%), MGA (ovarian carcinoma, 1.5%), PTEN (high-grade glioma, 14.2%), RB1 (lung adenocarcinoma, 5.0%), SMAD4 (ovarian carcinoma, 0.5%)." (PMID 34313788, 2021). "In ovarian cancer, CAF-derived exosomes express high levels of miR-98-5p that is transmitted to cells of the TME, leading to the development of cisplatin resistance by cancer cells through direct inhibition of cyclin-dependent kinase inhibitor 1A (CDKN1A, p21)." (PMID 32957712, 2020). "CAF-derived exosomes deliver miR-98-5p to ovarian cancer cells, contributing to cisplatin resistance by promoting cell proliferation and colony formation, and inhibiting cell apoptosis; CAF-derived exosome miR-98-5p targets CDKN1A, leading to its down-regulation in recipient ovarian cancer cells." (PMID 32957712, 2020).
gastric cancer (55 papers, 2008 to 2025). A primary or metastatic malignant neoplasm involving the stomach. "The TSPYL5 gene is of particular interest because, apart from the documented role as a putative TSG in glioblastoma and gastric cancer, it has been implicated in cancer signaling pathways involving CDKN1A (p21, WAF1/Cip 1) and pAKT in lung carcinoma cells." (PMID 28235398, 2017). "CDKN1A is associated with disease progression and prognosis in gastric cancer." (PMID 18827816, 2008). "In gastric cancer, it was shown that CDKN1A was epigenetically silenced by the HOXA-AS2-EZH2 complex." (PMID 38672246, 2024). "It has also been recently shown for cells of several types of cancer (glioma, pancreatic cancer, and stomach cancer) that the elevated expression of SOX9 leads to a decrease in CDKN1A and to the stimulation of cell division." (PMID 35884771, 2022). "And MNX-AS1, the antisense lncRNA of MNX1, was also reported to promote the invasion and metastasis of gastric cancer through repression of CDKN1A." (PMID 32850410, 2020). "Previous reports have shown PL causes cell cycle arrest in the G2/M-phase via induction of GADD45A in gastric cancer cells and G0/G1-phase arrest via elevation of CDKN1A expression in oral squamous cancer cells." (PMID 29535819, 2018). "By down-regulating FOXO3 and CDKN1A, miR-96-5p could promote the proliferation of gastric cancer cells and bladder cancer cells respectively." (PMID 36473369, 2023). "Moreover, the upregulation of CDKN1A and its frequently cytoplasmic relocation correlate positively with poor prognosis in gastric cancer." (PMID 35123499, 2022). "In contrast, CDKN1A inhibition by LincRNAFEZF1-AS1 promoted cell proliferation in gastric cancer." (PMID 33621203, 2021). "Cytoplasmic CDKN1A was reported to promote cell migration and invasion abilities in gastric cancer." (PMID 33621203, 2021). "LncRNA TINCR could bind to STAU1, influenced KLF2 mRNA stability, and regulated CDKN1A/p21 expression, thereby affecting proliferation and apoptosis of gastric cancer cells." (PMID 34234860, 2021). "Thus, up-regulation of CDKN1A was associated with cervical cancer and down-regulation of CDKN1C with gastric cancer." (PMID 32887258, 2020). "Interestingly, this lncRNA promotes gastric cancer cell proliferation by downregulating mRNA levels of CDKN1A in vitro and in vivo via binding with enhancer of zeste homolog 2 (EZH2)." (PMID 31514410, 2019). "We also found that mRNA expression levels of CDH1, CDKN1A, and EP300 were significantly reduced while those of RhoA, ROCK1, ROCK2, PIK3CA, and CCND1 were significantly increased in gastric cancers with reduced or loss of NKX6.3 expression compared to those in NKX6.3 positive cases." (PMID 30514953, 2018). "In addition, expression levels of CDH1, CDKN1A, and EP300 were reduced while expression levels of RhoA, ROCK1, ROCK2, PIK3CA, and CCND1 were increased in gastric cancer tissues with reduced or loss of NKX6.3 expression." (PMID 30514953, 2018). "Here, we hypothesized that CASC15‐miR‐33a‐5p‐CDKN1A/ZEB1 axis would be a novel pathway in gastric cancer." (PMID 29489064, 2018). "PRMT5 interacts with c-Myc and inhibits PTEN, CDKN2C (p18INK4C), CDKN1A (p21CIP1 or WAF1), CDKN1C (p57KIP2), and p63 gene expression to promote gastric cancer cell growth." (PMID 41154773, 2025). "Others have been reported to have good potential to be prognostic biomarkers for CRC (CDKN1A, CDKN1B), stomach cancer (MMP2,) and esophageal cancer (EGFR, PIK3CA,)." (PMID 35681633, 2022).
gastric cancer (continued). "Reduced levels of the transcription factor KLF2 decreases mRNA expression of two important target genes, cyclin-dependent kinase CDKN1A/P21 and CDKN2B/P15 (inhibitors of cell cycle checkpoints and cell proliferation) that promote gastric cancer cell growth." (PMID 34633481, 2021). "In gastric cancer, RUNX3 participates in TGF-β1-dependent cell growth suppression by binding to promoter p21 and inducing expression of CDKN1A (cyclin-dependent kinase inhibitor) that leads to inhibition of cancer cell proliferation." (PMID 34884658, 2021). "Previous reports have demonstrated that the miR-106b-25 cluster (miR-106b, miR-93, and miR-25), which is activated by E2F1, can inhibit the growth-suppressing functions of TGF-β signalling by interfering with the downstream mediators p21 (CDKN1A, Waf1/Cip1) and Bim (BCL2L11) in gastric cancer." (PMID 31728016, 2020). "In this study, we found that c-Myc could interact directly with PRMT5 to transcriptionally repress the expression of a cohort of genes, including PTEN, CDKN2C (p18INK4C), CDKN1A (p21CIP1/WAF1), CDKN1C (p57KIP2) and p63, to promote gastric cancer cell growth." (PMID 32292506, 2020). "For example, the oncogenic lncRNA linc01503 in gastric cancer interacts with zeste homolog 2 (EZH2) and lysine (K)-specific demethylase 1A (LSD1) enhancers, targeting the promoter regions of dual-specificity phosphatase 5 (DUSP5) and cyclin-dependent kinase inhibitor 1A (CDKN1A)." (PMID 41229433, 2025). "However, some genes (CHEK1, CDKN1A, CDKN2A, CCNB1, etc.)from the B-terms of the close discovery were cell cycle regulators, suggesting that anandamide might be related to cell cycle in gastric cancer." (PMID 24949851, 2014). "Results showed that expression levels of NKX6.3, CDH1, CDKN1A, and EP300 were decreased while expression levels of NFκB p65, AICDA, CBFβ, APOBEC3A, APOBEC3B, RhoA, ROCK1, ROCK2, PIK3CA, and CCND1 were increased in CagA positive gastric cancers compared to those in CagA negative cases." (PMID 30514953, 2018).
glioma (48 papers, 2002 to 2026). A benign or malignant brain and spinal cord tumor that arises from glial cells (astrocytes, oligodendrocytes, ependymal cells). "One such gene is CDKN1A, which encodes the cell cycle inhibitor p21 and which, on average, exhibits ~2-fold greater upregulation in HDACi-treated IDHmut glioma cultures." (PMID 41066183, 2025). "Previous studies showed that p21, a cyclin-dependent kinase inhibitor encoded by CDKN1A, plays a vital role in the senescence of glioma cells." (PMID 33869025, 2021). "In fact, the marker genes of the GABRA receptor families and cystine transporter xCT (SLA7A11 and CD44v), as well as antioxidation-controlled factors, such as JDP2, NRF2, and CDKN1A (p21Cip1), were significantly mutated in brain tumors, e.g., glioblastoma, glioma, and neuroblastoma." (PMID 39695141, 2024). "Changes in the SWI/SNF complex's stability, in turn, affect histone modifications in the glioma cells' CDKN1A promoter region, leading to TMZ drug resistance." (PMID 38600891, 2024). "This event gives rise to modified histone modifications in the CDKN1A promoter region, which subsequently impacts the biological activity of glioma cells." (PMID 38600891, 2024). "High CBX3 targets CDKN1A to promote the proliferation of U87 cells and predicts poor recurrence-free survival and OS in glioma patients." (PMID 34395271, 2021). "In this regard, it has been shown that FAM83H‐AS1 epigenetically silenced CDKN1A by binding to EZH2 in glioma cells." (PMID 32839509, 2020). "At the molecular level, one report showed that MET/EGFR signaling is regulated by FAM83H-AS1, and16 showed that FAM83H‐AS1 epigenetically silenced CDKN1A by binding to EZH2 in glioma cells." (PMID 32839509, 2020). "FAM83H-AS1 also contributes to bladder cancer cell proliferation, migration, and invasion, and to glioma progression by epigenetically silencing CDKN1A (p21)." (PMID 32074085, 2020). "In human cancers, overexpression of CDKN1A is frequently seen in carcinoma (prostate, cervix, breast, ovary, skin), brain tumor (glioma) and hematological malignancy." (PMID 25838973, 2015). "As a result, the data suggest that MAGED2 may increase the proliferation of glioma U251-MG cells by inhibiting CDKN1A." (PMID 35892426, 2022). "High CBX3 expression promoted glioma proliferation by targeting CDKN1A." (PMID 36292141, 2022). "We also discovered that MAGED2 regulates glioma U251-MG cell growth via CDKN1A." (PMID 35892426, 2022). "Furthermore, the downregulation of MAGED2 expression by MAGED2 CRISPR inhibited the proliferation of glioma U251-MG cells in vitro by upregulating CDKN1A." (PMID 35892426, 2022). "Finally, our findings showed that downregulating MAGED2 in vivo will decrease glioma tumor growth by increasing CDKN1A expression." (PMID 35892426, 2022). "As a result, the MAGED2/CDKN1A pathway may be related to the G1 phase of the cell cycle in glioma U251-MG cells." (PMID 35892426, 2022). "Significantly elevated levels of CDKN1A was found in the glioma tissues." (PMID 33621203, 2021). "The biological function of CDC42EP3 was correlated with DNA damage repair, and CDKN1A could be involved in the AKT pathway’s mediation of the TMZ resistance of glioma cells." (PMID 34834399, 2021). "We found that CDKN1A was involved in AKT-mediated TMZ resistance of glioma cells." (PMID 33621203, 2021). "In addition, silencing of miR-10b caused de-repression of CDKN1A/p21 by direct targeting its 3′ UTR and led to reduction of glioma cell growth." (PMID 31289362, 2019). "However, the expression level of both Cdkn1b and Cdkn1a was quite high in rat glioma 101.8." (PMID 41009560, 2025). "However, it is important to note that these data alone do not establish CDKN1A c.93C > A as a risk factor for glioma." (PMID 37730565, 2023).